DPP4 (dipeptidyl peptidase 4)
Diseases named in the same sentence as DPP4 in open-access papers (continued):
Sharing a sentence is not in itself a finding about the gene and the disease.
Obesity (continued). "Therefore, in terms of vascular protection, it seems reasonable to administer DPP-4 inhibitors to individuals with obesity who express high levels of DPP-4." (PMID 38256615, 2024). "Overall, these studies underscore the intricate relationships between DPP-4, glucose regulation, obesity, and inflammation, highlighting its complexity and interactions with bone metabolism, along with its regulatory mechanisms, suggesting potential therapeutic implications." (PMID 39054499, 2024). "DPP4, an adipokine secreted by adipocytes, is induced by inflammation and obesity." (PMID 39512972, 2024). "Furthermore, there was a positive correlation between serum miR-548ag and DPP4 levels in individuals with obesity." (PMID 38424257, 2024). "In addition, we have previously documented the pioneering discovery that elevated levels of adipose tissue-derived miR-548ag subsequent to obesity can induce an upregulation in Dipeptidyl Peptidase-4 (DPP4) expression within liver tissues." (PMID 38424257, 2024). "Based on these findings, it has been suggested that targeting DPP4 could be beneficial in managing obesity-related cardiometabolic diseases." (PMID 39335642, 2024). "DPP4 is considered an adipokine with a pleiotropic effect, whose levels are increased in conditions of obesity, insulin resistance and T2DM; it is also involved in lipid metabolism and in the atherosclerotic process.DPP4-i include sitagliptin, alogliptin, linagliptin and saxagliptin." (PMID 37842314, 2023). "DPP-4 was also identified as an adipokine potentially linking obesity and metabolic syndrome." (PMID 37371501, 2023). "Interestingly, a study has proved that hepatocyte-secreted DPP-4 promotes VAT inflammation and insulin resistance in obesity, while silencing the expression of DPP-4 in hepatocytes suppresses both inflammation of VAT and insulin resistance." (PMID 37371501, 2023). "Studies in mice using several tissue-specific targeting strategies have confirmed that the elevation of circulating DPP4 in obesity is liver derived, suggesting that DPP4 produced in the liver may primarily contribute to the progression of NAFLD." (PMID 36472923, 2023). "Here, we hypothesized that SFA such as PA is increased in asthma patients with obesity, which exacerbates type 2 airway inflammation in part by modulating IL-13-mediated release of soluble dipeptidyl peptidase 4 (DPP4)." (PMID 37287831, 2023). "Soluble DPP4 may have the therapeutic potential in asthma patients with obesity who have an endotype with mixed airway eosinophilic and neutrophilic inflammation." (PMID 37287831, 2023). "Moreover, in a lean mouse model of severe nonalcoholic fatty liver disease, phosphatidylethanolamine N-methyltransferase mice, we observed a 4-fold increase in circulating DPP4, in contrast with previous findings connecting DPP4 release and obesity." (PMID 36472923, 2023). "Targeting macrophage activation with the DPP4 inhibitor anagliptin has also been performed in genetically obese melanocortin 4 receptor-deficient (MC4R-KO) mice, which develop hepatic steatosis, NASH, and HCC in the presence of obesity and insulin resistance." (PMID 35053615, 2022). "The researchers suggest that plasma DPP-4 activity, which is elevated in the male offspring of mothers with obesity, may play an essential role here." (PMID 36077491, 2022). "Experimental evidence shows that, besides being a marker of AT inflammation and dysfunction, the DPP4, per se, elicits AT remodeling under stressful conditions, such as in the condition of chronic excessive caloric intake and obesity, and its inhibition reverts inflammation in animal models." (PMID 36140405, 2022). "The elevated plasma level of DPP4 strongly correlates with obesity-related MS." (PMID 36517853, 2022). "The increase in circulating levels of DPP-4 occurring during obesity could determine a pronounced inactivation of endogenous GLP-1, thus reducing the insulinotropic action of GLP-1 and consequently insulin secretion." (PMID 35628332, 2022).
Obesity (continued). "They indicate that DPP-4 inhibitor therapy during pregnancy could inhibit fetal programming toward obesity in the offspring of obese mothers, but more detailed research is required to confirm this observation." (PMID 36077491, 2022). "In addition to the role of DPP4 as an adipokine with the potential to induce insulin resistance, DPP4 expressed on dendric cells/macrophages play a critical role in potentiating inflammation of adipose tissue in obesity." (PMID 35053615, 2022). "Furthermore, DPP-4 expression is elevated in visceral fat in obesity, inflammatory conditions, and atherosclerosis." (PMID 35893426, 2022). "Taken together, miR-214 could be used as i) a potentially active biomarker for obesity and ii) targeting DPP4 to improve obesity-induced MS." (PMID 36517853, 2022). "Together, these studies suggest that targeting DPP4 could be effective for managing inflammation in obesity." (PMID 35909571, 2022). "Previous study demonstrate that DPP‐4 inhibitor treatment may prevent obesity through the activation of brown adipose tissue function." (PMID 35883204, 2022). "DPP4 also interferes with insulin signaling, reducing Akt phosphorylation, thus contributing to the development of insulin resistance; for all these reasons, the detection of elevated sDPP4 levels in the presence of obesity is somehow expected." (PMID 36140405, 2022). "Thus, expression and activity levels of DPP4 have been found to be altered in conditions such as obesity, T2DM, and non-alcoholic fatty liver disease (NAFLD), all of which indicate that analyses on DPP4 should take into account the context." (PMID 36197412, 2022). "Involvement of DPP-4 in metabolic control raises the possibility that it may play a role in metabolic diseases such as diabetes and obesity (Mulvihill and Drucker, 2014; Omar and Ahrén, 2014)." (PMID 33692997, 2021). "If one takes in consideration DPP4 overloading in obesity, increased DPP4 expression may favor SARS-CoV-2 entry in host cells in addition to altering the immunological and metabolic processes involved in COVID- 19 pathogenesis." (PMID 33816341, 2021). "This suggests that MIP-1α may be a substrate for DPP-4 and contributes to the regulation of macrophage polarization in obesity models." (PMID 33692997, 2021). "In the pro-inflammatory setting of obesity, activated intestinal intraepithelial lymphocytes might also upregulate the expression of molecules (such as dipeptidyl peptidase 4 (DPP4)) that degrade GLP1 as another means to reduce GLP1 bioactivity during obesity." (PMID 33972511, 2021). "Experimental obesity in mice showed greater DPP4 release compared to lean." (PMID 33816341, 2021). "In summary, DPP4 is abundantly expressed in various types of cells including T lymphocytes, adipocytes, hepatocytes, and smooth muscle cells, which triggers metabolic and immune responses in obesity-related metabolic complications and cancer patients." (PMID 33614513, 2021). "Moreover, a recent report showed the importance of hepatocyte-derived DPP-4 and obesity on adipose inflammation and insulin resistance." (PMID 33105604, 2020). "Therefore, it has been concluded that mainly hepatocyte-derived dpp4 promotes inflammation and insulin resistance in obesity, potentially also through auto- and paracrine mechanisms." (PMID 31794591, 2019). "More recently, DPP-4 has been found to have effects on metabolic control, raising the possibility that it may play a role in metabolic diseases such as diabetes and obesity." (PMID 30828317, 2019). "The finding that hepatocyte-secreted dpp4 is dispensable for incretin cleavage and glucose control in diabetic mice may be extended to conditions of obesity and hyperglycemia." (PMID 31794591, 2019). "Actually, DPP4 expression is upregulated in adipose mononuclear immune cells in obesity-induced IR, which may help to a rapid DPP4-mediated degradation of incretin peptides via its enzymatic function." (PMID 31581657, 2019).
Obesity (continued). "Soluble DPP4 has previously been identified as cytokine related to obesity." (PMID 31208420, 2019). "Our work is the first to consider the DPP-4-like activity of the gut microbiota as a potential target of DPP-4 inhibitors and evaluate, in an animal model of diet-induced obesity, the effect of vildagliptin on gut barrier function, innate immune response and liver." (PMID 29797022, 2018). "In addition, DPP-4 expressed in dendritic cell/macrophages contributes to potentiating inflammation of adipose tissue in obesity." (PMID 29669555, 2018). "Therefore, although further investigation is important, the potential utility of DPP‐4 inhibitors for the treatment of a broad spectrum of metabolic disorders related to obesity via the activation of BAT function in humans is still of interest." (PMID 30410858, 2018). "Therefore, our study reveals a cross talk between AT1R signaling and DPP4 activation in the regulation of megalin and underscores the significance of targeting DPP4 in the prevention of obesity related kidney injury progression." (PMID 27213360, 2016). "Thus, DPP-4 is a novel adipocytokine and biomarker, and it is a potential link between obesity and the metabolic syndrome." (PMID 27652270, 2016). "We also assessed the effects of DPP-4 inhibition in IRS-1 deficient mice fed an SL or SO diet as a model of insulin resistance without obesity." (PMID 26937254, 2016). "High DPP4 activity might induce subsequent accumulation of body fat and increased BMI, and in turn long-term obesity and lipid accumulation will lead to insulin resistance and hyperglycemia via abnormally obesity-linked down-regulation of adiponectin." (PMID 26415691, 2015). "Mice lacking the gene encoding DPP4 are refractory to the development of obesity and hyperinsulinemia and demonstrate improved post-prandial glucose control." (PMID 26441982, 2015). "Emerging evidence, combined with our findings, supports the hypothesis that DPP4 could be a significant protein for adipose tissue remodeling with possible impact on obesity and metabolic diseases." (PMID 25816202, 2015). "Furthermore, DPP4 release strongly correlates with adipocyte size, potentially representing an important source of DPP4 in obesity." (PMID 23853775, 2013). "Moreover, elevated DPP-4 activity is observed in obese patients, which may suggest its potential link to the pathogenesis of obesity." (PMID 38339106, 2024). "These authors discussed the presence of circulating soluble DPP-4—a DPP-4 form distinct from the enzymatic DPP-4—and proposed that while enzymatic DPP-4 may be linked to obesity-associated inflammation and glucose regulation, soluble DPP-4 may have separate functions unrelated to inflammation." (PMID 39054499, 2024). "In conclusion, DPP-4 has a neutral effect on weight or a minor reduction in weight, acarbose has mild effects, metformin and SGLT-2 inhibitors have moderate effects on weight loss, and some of the GLP-1 agonist drugs have the strongest and most promising results as anti-obesity drugs." (PMID 37109541, 2023). "Previous studies reported that DPP4 inhibitors could ameliorate high-fat diet-mediated obesity-related glomerulopathy, which may relate to the improved insulin sensitivity and reduced local inflammation through inhibiting macrophage infiltration and IL-6 and TNF-α secretion." (PMID 35935760, 2022). "Hence, it is conceivable that most peptides with anti-obesity activity may have similar characteristics as those displayed by DPP-4 inhibitory peptides." (PMID 35204214, 2022). "Thus, it is intriguing to test in the future whether EA could be potentially a more effective anti-diabetic and anti-obesity agent than some of the currently prescribed monotherapeutic drugs such as DPP4 inhibitors, metformin, and GLP-1 analogs." (PMID 36386896, 2022).
Obesity (continued). "Importantly, the DPP4 inhibitor linagliptin induced a reciprocal decrease in M1 macrophages and an increase in M2 macrophages in white adipose tissue and liver tissue of mice, resulting in attenuation of obesity-induced inflammation and insulin resistance." (PMID 35053615, 2022). "Hence, use of DPP-4 inhibitors may be effective treatment to fight with metabolic impairments of obesity." (PMID 36419097, 2022). "In addition, DPP4 also plays a non-enzymatic role in regulating immune cells and the AT inflammation associated with obesity and diabetes." (PMID 35909571, 2022). "Moreover, DPP4 inhibition reduces M1-polarized macrophage migration while inducing the M2 phenotype in AT and the liver via macrophage inflammatory protein-1α, thereby attenuating obesity-induced inflammation and insulin resistance." (PMID 35909571, 2022). "Interestingly, DPP4 is upregulated in obesity, especially in the insulin resistance state." (PMID 32806722, 2020). "Besides its upregulation in T2DM and obesity, DPP4 expression is increased in senescent cells." (PMID 32848769, 2020). "Additionally, serum miR-214 expression was demonstrated to be negatively correlated with serum DPP4 concentration and the HOMA-IR, indicating that the aberrant expression of miR-214 might be involved in the development of obesity-associated IR." (PMID 32093712, 2020). "Accordingly, excess DPP-4, derived from adipocytes and/or hepatocytes, may act as a local mediator of inflammation and adipose/hepatic tissue insulin resistance, thereby forming one link between obesity and the pathogenesis of T2DM and metabolic disease." (PMID 30828317, 2019). "Thus, plasma DPP4 activity in T2DM serves as an obesity independent parameter." (PMID 31402899, 2019). "Moreover, our therapeutic strategy using NL@Cas9-RNP to target DPP-4 can be used for other diseases as well given that DPP-4 is known to exert substantial pleiotropic effects for a variety of diseases such as obesity, chronic renal disease, cardiovascular disease, and inflammation." (PMID 30696428, 2019). "There were significant differences in the frequency of receiving metformins, TZDs, DPP4 inhibitors, ARBs, CCBs, Beta blockers, statins, UA lowering agents and anti-platelet agents among the four categories of body composition, when using BMI for the classification of obesity." (PMID 29636045, 2018). "However, the molecular mechanisms underlying this anti‐obesity phenotype in DPP‐4‐deficient mice have not been fully clarified." (PMID 30410858, 2018). "Moreover, circulating DPP4 is increased in obese and type 2 diabetic subjects, and it may be a link between obesity and vascular dysfunction." (PMID 29958403, 2018). "Interestingly, DPP-4 itself is reportedly an obesity-related adipokine that might worsen insulin resistance." (PMID 26937254, 2016). "Thus, it can be speculated that DPP4 might also play an important role in the chronic low-grade inflammation taking place in obesity and T2DM." (PMID 26284071, 2015). "Importantly, circulating DPP4 is augmented in obese and type 2 diabetic subjects, and it may represent a molecular link between obesity and vascular dysfunction." (PMID 26284071, 2015). "Thus, insulin-independent diabetes associated with obesity, which have perturbed leptin receptor and/or MC4R signaling, may be resistant to the DPP-4 inhibitor." (PMID 24804243, 2014). "The authors suggested that DPP4 may be a novel biomarker linking obesity to MetS." (PMID 23379505, 2013). "NAH derivatives with anti-obesity activity and improved safety profiles, dual COX/LOX-modulating NAHs and β-amino-NAHs acting as DPP-4 inhibitors illustrate the versatility of this scaffold in addressing complex, multifactorial diseases." (PMID 41596477, 2026). "Outcomes of the traditional and all obesity‐related cancers with metformin, GLP1‐RA or dual treatment compared with DPP4 inhibitor." (PMID 41178701, 2026).
Obesity (continued). "Bacteroides acidifaciens has been reported to activate proliferator-activated receptor α (PPARα) and inhibit dipeptidyl peptidase-4 (DPP-4) secretion, resulting in anti-obesity effects." (PMID 40650060, 2025). "Linagliptin, another DPP4 inhibitor, was suggested to have a cardioprotective role through FGF-2/EGR-1 pathway in mice with dietary obesity, and capillary rarefaction was suggested to be important in this process." (PMID 41463358, 2025). "There are more patients taking oral anti-diabetic agents including metformin, dipeptidyl peptidase IV inhibitor (DPP4 inhibitor) and sodium-glucose co-transporter 2 inhibitor (SGLT2i) in the obesity group." (PMID 39058301, 2024). "Studies have shown that plasma DPP-4 is elevated in children born to mothers who are obese during pregnancy, with animal models revealing that DPP-4i can prevent the development of obesity in offspring." (PMID 38339106, 2024). "Given the success of incretin-based drugs in treating both diabetes and obesity, and their potential for treating NAFLD, further dissection of the regulation of hepatic metabolic pathways by DPP4 is warranted." (PMID 36472923, 2023). "On the other hand, dipeptidyl peptidase 4 (DPP-4), an enzyme secreted from PVAT, degrades GLP-1 and has been suggested as a pathophysiological link between obesity and cardiovascular diseases." (PMID 37627590, 2023). "It has been shown that the adipocyte membrane receptors ACE2, DPP4 and CD147 as well as the expression of SARS-CoV-2 entry protease-furin are upregulated in patients with obesity." (PMID 37867515, 2023). "Dipeptidyl peptidase 4 (DPP4), an adipokine released by hepatocytes, is known to be upregulated in the liver of patients with obesity and NAFLD, while methylated DPP4 is negatively correlated with the stages of hepatic steatosis and NASH." (PMID 37361533, 2023). "Obesity is characterized by a higher expression of dipeptidyl-peptidase 4 (DPP4) compared to the lean subject, thus showing more DPP4 activity in cases of obesity." (PMID 36517853, 2022). "The levels of plasma DPP4 activity are elevated in diseases, including T2DM, obesity, chronic diabetic kidney disease, cardiovascular diseases and atherosclerosis." (PMID 35630534, 2022). "Expression of alternative SARS-CoV-2 entry receptors like CD147, dipeptidyl peptidase 4 (DPP4), and neuropilin 1(NRP1) have been reported in adipocytes and their expression is increased by obesity and decreased by anti-inflammatory myokines." (PMID 36137009, 2022). "Undoubtedly, further research on the use of DPP-4 inhibitors in the treatment of GDM and their possible impact on reducing fetal programming for obesity and metabolic diseases." (PMID 36077491, 2022). "Other nominally significant associations were established between WHOCS scales and: IFNL4 rs12979860, ACEIs, obesity, ARA-II, HCP5 rs2395029, ACE rs1799752, DPP4 rs17574, HMOX1 rs2071746, IL10 rs1800896, IL6 rs1818879, NFKB1 rs28362491, and MX1 rs469390." (PMID 35636966, 2022). "Patients receiving SGLT2 inhibitors were more likely to have high levels of hyperlipidemia and obesity and to be simultaneously receiving GLP-1 agonists, insulin, metformin, and statins compared with those receiving DPP4 inhibitors." (PMID 34797368, 2021). "As native OXM has a very short half-life due to degradation by DPP4 and fast renal clearance, OXM analogues are being developed as a therapeutic candidate to treat obesity and T2DM." (PMID 34072172, 2021). "Dipeptidyl peptidase 4 (DPP4), an adipokine released by hepatocytes, is known to be upregulated in the livers of patients with obesity and NAFLD." (PMID 33143364, 2020). "In summary, our study supports a newly described pleiotropic protective effect of DPP-4 inhibitor SIT on diastolic function and β-cell function in the obesity female mouse model." (PMID 30116740, 2018).